NOS3 (nitric oxide synthase 3)
Diseases named in the same sentence as NOS3 in open-access papers (continued):
Sharing a sentence is not in itself a finding about the gene and the disease.
Hypertension (continued). "Indeed BH4 doubled NOS3 activity in a concentration-dependent manner in homogenates of first trimester and term placenta and uncoupled NOS3 and oxidative stress in a rat model of pregnancy-induced hypertension." (PMID 25303561, 2015). "Additional studies examining the aorta after pharmacologic treatment to induce hypertension (angiotensin II or phenylephrine infusion) of Notch1+/− and Notch1+/−; Nos3−/− may give a more definitive picture of the role on Notch1 in this disease." (PMID 25914885, 2015). "Variation in NOS3 has also been tested for hypertension and diabetes." (PMID 24806096, 2014). "Some, but not all studies, show that NOS3 polymorphisms leading to lower NO production are associated with hypertension and/or preeclampsia." (PMID 22848831, 2012). "However, our suggestive pharmacogenetic associations argue for future genetic and functional studies to confirm our findings and explore the implications of NOS3 genetic variation in hypertension treatment with respect to cardiovascular outcomes." (PMID 22470539, 2012). "The association between NOS3 gene polymorphisms and essential hypertension is not clear yet, and there are only a few studies investigating the association of these polymorphisms with resistant hypertension." (PMID 19650939, 2009). "However, no consensus has been reached on the relationship between NOS3 gene polymorphism and hypertension is debatable." (PMID 36758021, 2023). "In addition, sodium-rich diet, high alcohol intake, genetic modification of the NOS3 (Nitric Oxide Synthase 3) gene and ADD1 (Adducin 1), could explain the high prevalence of hypertension in this same population as they are risk factors." (PMID 37824544, 2023). "Therefore, we hypothesized that the renal lesions exhibited by ApoE/NOS3−/− mice were possibly due to a combination of hypertension and reduced salt sensitivity." (PMID 36360235, 2022). "Moreover, ADMA has a negative impact on the endothelial-NO synthase 3 (NOS3) based on the dysfunction of endothelial cells associated with a variety of diseases including coronary artery disease, diabetes mellitus, and hypertension." (PMID 34236536, 2021). "Interestingly Nos3−/− mice have been described to also exhibit high blood pressure." (PMID 32801116, 2020). "Unfortunately, we did not have available data about hypertension due to the retrospective nature of the study, but given the possible correlation between NOS3 polymorphisms and hypertension, it will be interesting to evaluate this in our ongoing prospective study." (PMID 31330833, 2019). "Up-regulation of NOS3 also could be a compensatory response to counteract the hypertension." (PMID 24722050, 2014). "When balancing HT risks and benefits in early postmenopausal women with CV risk factors such as diabetes and hypertension, ESR1 Pvull, NOS3 G894T and T-786C polymorphism analysis may be considered in relation to endothelial-mediated benefits, fundamental in atherosclerosis progression process." (PMID 25077953, 2014). "Nevertheless, we were able to found significant effects of different genotypes for NOS3 rs3918226 and GUCY1A3 rs7692387 on nitrite concentrations in hypertensive disorders of pregnancy." (PMID 38469120, 2024). "Both upregulated gene expressions (e.g., NOS3) and downregulated gene expressions (e.g., ACE) are shown here for this hypertension example with nutrient and ranking information also provided." (PMID 37305078, 2023). "In the dominant model of oxidative stress (NOS3: GG + IGFBP3: GG vs NOS3 GT + TT; IGFBP3: AG + AA), women had a prevalence of 34.7% hypertension (PR = 1.42; 95% CI 1.12–1.79; p = 0.003)." (PMID 34001234, 2021). "The findings of this work revealed that, by comparison to the control group, the L-NAME group had significantly lower levels of SOD, NOS3, and GSH, which contributed to the development of hypertension." (PMID 32765804, 2020).
Hypertension (continued). "NOS3 should be studied further for its effects on PEH in a large, ethnically diverse sample of adults with hypertension to confirm our findings." (PMID 29180482, 2017). "The univariate analysis revealed that the NOS3 VNTR, age and hypertension contributed to the advancement of CKD." (PMID 25340172, 2014). "Our results place NOS3 gene as the common nexus between CAD, CVD and hypertension, with serum lipids connected to CVD through SLC22A2, in combination with TOMM40 for CAD and to hypertension through HLA-DQA1." (PMID 39258111, 2024). "However, it is difficult to separate the effects of diabetes, arterial hypertension, and medication from the effects of CAD on miRNA expression and NOS3 levels." (PMID 37239987, 2023). "This study demonstrates that the absence of adipocyte NOS3 potentiates diet-induced hypertension and reveals chemerin as a molecular link between adipose tissues and the vasculature." (PMID 37897505, 2023). "Based on meta-analyses, A2ML1 was related to hypertension; ADRB2 and NOS3 jointly acted on sympathetic nervous system; while ADRB2 was related to hypertension in American Indians and involved in pathophysiology of hypertension in Yi population." (PMID 34297769, 2021). "However, in the recessive model of oxidative stress (NOS3: TT + IGFBP3: AA vs NOS3: GG + GT IGFBP3: GG + AG), they had a prevalence of 77.0% hypertension (PR = 2.07; 95% CI1.78–2.42 p < 0.001)." (PMID 34001234, 2021). "Back to the compound target network, luteolin and quercetin were found to influence NOS3 and NOS2 tested targets directly for hypertension, future studies should recognize the role of these compounds in CIF, and pharmacokinetic parameters should be calculated in both healthy and disease." (PMID 34055010, 2021). "The SNPs in the NOS3 rs1799983, IGFBP3 rs11977526, and TCF7L2 rs7903146 genes can directly influence the protein expression in the respective genes, making them important biomarkers for the development of hypertension." (PMID 34001234, 2021). "Moderate hypertension was identified in nondiabetic female Nos3‐/‐ mice (SBP: 129 ± 3 mmHg) and was equivalent to nondiabetic males (SBP: 130 ± 5 mmHg)." (PMID 31535473, 2019). "We also included known hypertension-related genes, including AGTR1, NOS3, and CSF1." (PMID 27779208, 2016). "Multivariate analysis revealed that a positive history of hypertension, the AGT TT genotype, the NOS3 GA+AA genotype, and a pre-pregnancy BMI of 24 or higher were independently associated with severe PIH (Odds ratios (ORs): 2.53, 1.78, 2.21, and 2.44, respectively)." (PMID 19838007, 2009). "Therefore, MR signalling in macrophages promotes dysfunction in the diabetic heart and kidneys of Nos3-/- mice without affecting hypertension." (PMID 41332229, 2025). "Moreover, Suvorava and colleagues have shown that Nos3−/− rescue through additional NO supplementation does not result in reduced hypertension in 3- to 4-month adult Nos3−/− mice, supporting an extra-endothelial role of Nos3." (PMID 32801116, 2020). "A whole genome-scan meta-analysis for preeclampsia has already identified the locus of NOS3 gene as a promising candidate for preeclampsia susceptibility, although linkage studies seem to support a relationship between NOS3 and hypertension rather than preeclampsia." (PMID 22051068, 2011). "Hence, several investigators have examined the NOS3 gene as a potential candidate for essential hypertension, but its relation with resistant hypertension has not been verified." (PMID 19650939, 2009). "Of particular interest are the SNPs within the NOS3 (endothelial nitric oxide synthase), F5 (Leiden factor), TNFSF4 (cytokine pathway), and CDKN2B-AS1 (cell cycle regulation) genes, which may play a key role in the development of vascular dysfunction and hypertension in this pathology." (PMID 40507612, 2025).
atherosclerosis (146 papers, 1997 to 2025). A disease characterized by the build-up of fatty material and calcium deposition in the arterial wall resulting in partial or complete occlusion of the arterial lumen. "In the Chr 5 locus, there are 4 hepatic genes with eQTL that are in strong LD with the atherosclerosis associated SNP at the locus: Nub1 (p = 1.65×10−16), Nos3, (p = 3.08×10−6), Cdk5 (p = 2.48×10−5), and Abcb8 (p = 7.46×10−4)." (PMID 26694027, 2015). "NOS3 protein was initially found to participate in NO generation, mainly in endothelial cells, and is associated with cardiovascular diseases such as hypertension, atherosclerosis, and diabetes mellitus." (PMID 33747912, 2021). "Lox-1 upregulation is observed in atherosclerosis and linked to oxidative stress and inflammatory reactions leading to inhibition of Nos3 enzymatic activity via increased C-reactive protein production and, consequently, microvessel dysfunction in the periphery." (PMID 30410436, 2018). "More chronically, NOS3 may become dysregulated (‘uncoupled’) and produce potentially harmful superoxide anions, resulting in chronic oxidant stress that is implicated in the pathogenesis of atherosclerosis." (PMID 19132087, 2009). "Concurrently, IFN signaling suppresses endothelial nitric oxide synthase (NOS3) expression and nitric oxide production, enhancing proinflammatory leukocyte recruitment to the arterial wall and exacerbating the progression of atherosclerosis." (PMID 41359111, 2025). "Network pharmacology and molecular docking analyses indicated that AKT1 and NOS3 (also known as eNOS) play crucial roles in GE alleviating atherosclerosis." (PMID 40718724, 2025). "The evidence that IL-10 and NOS3 play a positive role in inhibiting the development of atherosclerosis has been discussed elsewhere." (PMID 35059464, 2022). "And research has reported that NOS3 is mainly upregulated in endothelial progenitor cells (EPCs) of the spleen, exerting beneficial functions on atherosclerosis, angiogenesis, and vascular repair." (PMID 33747912, 2021). "As expected, we observed that laminar shear stress induces cell shape change, up‐regulates vasoprotective genes (such as CPY1B1, THBD and NOS3) and, however, down‐regulates pro‐atherosclerosis genes (such as VCAM1, CD36, and ANGPT2)." (PMID 34085389, 2021). "We also observe a decrease in the number of NOS3-expressing endothelial cells in samples with highly advanced atherosclerosis." (PMID 34202347, 2021). "ARG2 is associated with nitric oxide synthase 3 (NOS3)/eNOS dysfunction in the pathogenesis of vascular aging and atherosclerosis." (PMID 34943028, 2021). "In those with severe KD, NOS3 is expressed in coronary artery aneurysm tissue removed at surgery, and the tissue shows a pattern of senescence that is also typical of atherosclerosis." (PMID 19132087, 2009). "Decreased KLF4 activity alters the expression of its downward transcription targets, such as decreased nitric oxide synthase 3 and thrombomodulin, and increased monocyte chemoattractant protein‐1, making the vascular environment prone to inflammation and atherosclerosis." (PMID 36807865, 2023). "While many immune pathways were enriched in the upregulated DEGs (e.g., CXCR5, IL21R, CCR7 and CD22) (A,C), pathways such as “lipid and atherosclerosis’ and “fluid shear stress and atherosclerosis” were enriched in the downregulated DEGs (such as NOS3, KLF2 and KLF4)." (PMID 37218991, 2023). "ApoE/NOS3−/− mice had more severe hepatic steatosis and atherosclerosis than ApoE−/− mice." (PMID 36360235, 2022).
atherosclerosis (continued). "In this study, we crossed the ApoE knockout (ApoE-KO; ApoE−/−) atherosclerotic mouse model with the NOS3 knockout (NOS3-KO; NOS3−/−) hypertensive mouse model to establish an ApoE/NOS3 double knockout (ApoE/NOS3-KO; ApoE/NOS3−/−) hypertensive atherosclerosis mouse model." (PMID 36360235, 2022). "Furthermore, epigenetic changes were also identified in several genes including RELA (RELA Proto-Oncogene, NF-KB Subunit), NOS3 (Nitric Oxide Synthase 3), KLF4 (KLF Transcription Factor 4) and APOE (Apolipoprotein E) that have been linked to progression of atherosclerosis." (PMID 37190071, 2023). "It is assumed that the constitutively expressed endothelial nitric oxide synthase (eNOS or NOS3) is responsible for maintaining and improving endothelial function during chronic inflammatory conditions such as atherosclerosis or stenosis." (PMID 39913351, 2025). "Subsequently, genes related to the atherosclerosis indicators EDN1, PTGIS, AGT, NOS3, ICAM1, and VCAM1 were detected by qPCR." (PMID 36180828, 2022). "At high degrees of advancement of atherosclerosis, the endothelium was damaged and disintegrated, with no signs of NOS3 expression." (PMID 34202347, 2021). "Xing Shasha established a mouse model of atherosclerosis through high-fat diet, and treatment with SAL effectively improved the skin function and reduced the atherosclerotic lesion area; these beneficial functions may be attributed to NO production and AMPK/PI3K/Akt/NOS3 pathway activation." (PMID 38968273, 2024). "So, RAB5A may be involved in the pathogenesis of atherosclerosis by changing the proliferation and migration function of endothelial cells through some cytokines and/or signaling pathways, such as the interferon response, Notch signaling pathways, VEGFR2, VE-cadherin, NOS3, and IL-10." (PMID 35059464, 2022). "In the absence of NOS3, increased transcriptional expression of EMMPRIN may allow accumulation of high glycosylated forms of EMMPRIN, which help to explain the levels of MMPs in human and murine atherosclerosis." (PMID 30347750, 2018).
diabetes (122 papers, 2006 to 2026). "Multivariable logistic regression models were used to examine the association of sequence variation in the NOS3 gene and diabetes case status." (PMID 24278136, 2013). "In the present work, we sought to investigate the effect of estrogen on NOS-3 associated vascular function in a streptozotocin (STZ)-induced diabetes model and the underlying mechanisms related to the ERα/NOS-3 signaling network." (PMID 23209733, 2012). "Another meta-analysis could not determine an association between diabetic retinopathy in patients with type 2 diabetes mellitus and NOS3 27-bp VNTR 4b/a genetic polymorphism." (PMID 40142738, 2025). "Moreover, there are reports about the potential role of NOS3 polymorphisms in the development of diabetes complications." (PMID 39061907, 2024). "The NOS3 gene has been linked with diabetes and nitric oxide (NO) bioavailability, which influences endothelial function and contributes to vascular complications in diabetes." (PMID 34960114, 2021). "Dysfunction of Nos3 signaling has also been implicated in EPC dysfunction in diabetes." (PMID 29995913, 2018). "NOS3 is encoded by the NOS3 gene located on chromosome 7q35-36 and three polymorphisms (G894T, 4b/a, and T786C) in the NOS3 gene are associated with diabetes and diabetes related traits and reduced enzyme activity and consequently bioavailability of NO and endothelial function." (PMID 27990443, 2016). "NOS3 G894T genotype and allele frequencies stratified by race and diabetes case status." (PMID 24278136, 2013). "Association of NOS3 genotype and diabetes case status in African Americans stratified by obesity." (PMID 24278136, 2013). "Association of NOS3 genotype and diabetes case status in whites stratified by obesity." (PMID 24278136, 2013). "NOS3 emerged as a cross-regional hub gene modulating diabetes-related AGE-RAGE pathways, exhibiting demonstrable regional specificity." (PMID 40710523, 2025). "Table showing genotypic (GG, GT, TT) frequencies of the NOS3-G894T polymorphism among STEMI (n=71), STEMI with diabetes (n=77), and healthy controls (n=75)." (PMID 40144407, 2025). "Table showing allele (G, T) frequencies of the NOS3-G894T polymorphism among STEMI (n=71), STEMI with diabetes (n=77), and healthy controls (n=75)." (PMID 40144407, 2025). "The study found a strong link between the G894T NOS3 TT genotype and increased STEMI risk, especially in patients with diabetes." (PMID 40144407, 2025). "The nitric oxide synthase gene NOS3 is connected with diseases such as Alzheimer’s disease, diabetes mellitus, coronary artery disease, and malignant neoplasms of the breast, highlighting its role in vascular function and oxidative stress." (PMID 39337647, 2024). "Real‐time PCR analysis show marked increases in kidney fibronectin, TGFβ, smooth muscle actin, and E‐cadherin following diabetes in NOS3−/− mice." (PMID 33713581, 2021). "Diabetic NOS3−/− mice displayed an increased percent of fibrosis (using ImageJ) in Masson's trichrome ‐stained sections 24 weeks after diabetes, which was reduced by treatment with homoarginine." (PMID 33713581, 2021). "The rs5186, rs1800629, rs1799983 and rs1800795 variants in the AGTR1, TNFA, NOS3 and IL6, respectively, are therefore relevant to diabetes and associated complications." (PMID 33820928, 2021). "Diabetic NOS3−/− mice displayed a marked increase in infiltrating kidney macrophages following diabetes compared with non‐diabetic mice." (PMID 33713581, 2021). "Diabetes significantly increased albuminuria in both wild type and NOS3−/− mice compared with normal, an effect significantly reduced by homoarginine treatment." (PMID 33713581, 2021). "The aim of this study is to quantify global DNA methylation and investigate the relationship with diabetes status and polymorphisms in MTHFR C677T and NOS3 G894T genes in mixed ancestry subjects from South Africa." (PMID 27990443, 2016).